INS (insulin)
Diseases named in the same sentence as INS in open-access papers (continued):
Sharing a sentence is not in itself a finding about the gene and the disease.
insulinoma (continued). "Contrastingly, the increased length of G1 may allow time to respond to external signals and to accumulate differentiation-inducing transcription factors, which could explain the characteristic of insulinomas to keep the ability to secrete insulin as normal differentiated beta cells." (PMID 29853883, 2018). "This stimulates insulin secretion more than low-carbohydrate diets, and could exhaust the β-cells after a few years of consumption of such a regimen, and lead to lethargy and insulinoma." (PMID 29403642, 2018). "The difference observed in glucose tolerance and insulin sensitivity could be due to the presence of melatonin in the DL session, as melatonin has been reported to inhibit insulin secretion in both rat insulinoma cells and pancreatic islets, thus influencing blood glucose." (PMID 28270559, 2017). "However, insulin levels were appropriately suppressed [9 mcIU/mL (reference range: <18 mcIU/mL)], and C-peptide levels were low as well [0.2 ng/mL (reference range: 1.0–7.6 ng/mL)], a finding felt to be inconsistent with an insulinoma." (PMID 26346767, 2015). "We report the case of a patient with a metastatic malignant insulinoma treated with intermittent everolimus, obtaining an important improvement in the quality of life; this suggests the necessity of preclinical studies to analyze the cellular pathways involved in insulin-independent gluconeogenesis." (PMID 25298880, 2014). "The insulinoma component may have been growing slowly, so not enough insulin was being secreted to cause initial symptoms." (PMID 26425568, 2013). "Most insulin-mediated hypoglycaemia is due to either exogenous insulin use or the presence of an insulinoma but in recent years, the differential diagnosis has expanded to include other forms of beta cell dysfunction, some of which may simulate insulinoma, as illustrated in the following case." (PMID 20615254, 2010). "Sodium tungstate has also been shown to exert insulin-mimetic effects in isolated hepatocytes and to increase insulin content and enhance insulin secretion in the presence of glucose and various segretagogues in an insulinoma cell line and the perfused pancreas." (PMID 19715561, 2009). "Stimulation of mouse primary beta cells or MIN6 insulinoma cells with glucose led to oscillatory InsP3 generation that was tightly coupled with calcium increase, but was found not to be the driving force for the calcium oscillations that led to insulin release." (PMID 19680544, 2009). "To assess whether the modification of UCP2 activity observed in patients 1 and 2 could affect insulin secretion in beta cells, we subjected an insulin-secreting pancreatic insulinoma cell line (INS-1E) to adenoviral expression of wild type and mutated UCP2 in mitochondria." (PMID 19065272, 2008). "To corroborate this, we also used the rat insulinoma cell line INS-1, which exhibits an inherently high glucose-stimulated insulin secretion, overcoming the requirement of proinsulin co-transfection." (PMID 40789936, 2025). "The protective effects of TXM peptides against AuF-induced apoptosis were evaluated in the rat insulinoma INS-1832/13 cell line, which contains a human insulin expression cassette enabling secretion of human insulin." (PMID 41129928, 2025). "The present study provides two novel findings: (i) serum LEAP2 concentrations are significantly elevated in patients with insulinoma and correlate with insulin levels, and (ii) LEAP2 peptide is extensively expressed in insulinoma tissues." (PMID 41488138, 2025). "Using another antibody, we performed colocalization for LEAP2 and insulin via immunofluorescence staining, and we found a strong positive signal of LEAP2 within the insulinoma cells, confirming the expression of LEAP2 peptide in tumor cells." (PMID 41488138, 2025). "Therefore, GLP- 1R expression might also be associated with insulin secretion in PanNETs, particularly insulinomas; however, this association has not been explored in detail." (PMID 40281248, 2025).
insulinoma (continued). "For example, inhibition of CPT1A with etomoxir produced an increase in insulin secretion in insulinoma cells, and conversely, when CPT1A was overexpressed in insulinoma cells, GSIS was decreased." (PMID 39814231, 2025). "For the in vitro study, isolated pancreatic islets of mice and cells of a rat insulinoma cell line (INS-1) were stimulated with ≤20 μM MK-4 for a maximum of 1 h, leading to a statistically significant increase in insulin secretion in both cases." (PMID 40944124, 2025). "This approach can be broadly applied to any cell type and organelle beyond the scope of our model system of insulin vesicles and INS-1E insulinoma cells." (PMID 39190030, 2024). "Prolonged proline exposure increased basal insulin secretion and decreased glucose-stimulated insulin secretion in both clonal INS1-E insulinoma cells and isolated rat islets." (PMID 38422035, 2024). "We investigated the effect of adropin on insulin and glucagon secretion using pancreatic tissue fragments of normal and diabetic rats and the INS-1 832/3 rat insulinoma cell line." (PMID 39337311, 2024). "In mouse primary pancreatic islet cells and cultured rat insulinoma INS-1E cells, SA inhibited insulin secretion by stimulating miR-34a-5p to suppress the expression of BCL2 and BCL-W, showing stronger lipotoxic effects than other fatty acids." (PMID 38501107, 2024). "Pancreas sections derived from Whipple procedures of two insulinoma patients were stained for INS-DRiP, insulin, and glucagon." (PMID 38596681, 2024). "Our previous studies demonstrated that ISCs regulate insulin secretion and apoptosis in the MIN6 insulinoma cell line via the secretion of Wnt5a and activation of the FoxO1‐PDX1‐GLUT2‐insulin signaling cascades." (PMID 38185936, 2024). "Glucose increases the S1P content by activating SphK2 in mouse insulinoma MIN6 cells and mouse pancreatic islet cells, whereas SphK2 knockdown reduces glucose-stimulated insulin secretion." (PMID 38256005, 2024). "In insulinoma cells, exposure to PEMF attenuated insulin secretion, suggesting effects on the calcium channels and ion flux." (PMID 36981580, 2023). "For this purpose, BCL-XL was overexpressed in two β-cell lines—namely, rat insulinoma-derived INS-1E and human insulin-producing EndoC-βH1 cells—using adenoviral vectors." (PMID 36982731, 2023). "Therefore, our primary aim was to compare serum insulin concentration in dogs with insulinoma and WHO stage I disease to those with WHO stage II or III disease and to establish if an association existed between stage and other variables and serum insulin concentrations at the time of diagnosis." (PMID 37194422, 2023). "We tracked two insulin granule membrane proteins, phogrin and zinc transporter 8, fused to HaloTag in rat insulinoma INS-1 cells and, by evaluating the tracks with mean-square displacement, demonstrated the characteristic behavior of insulin granules." (PMID 38124716, 2023). "The mouse insulinoma MIN6 cell line has consistent proliferation into high passages (<80) and releases mouse insulin in response to glucose." (PMID 38162632, 2023). "A similar inverse relationship exists in another rat insulinoma cell line (RIN m5F), in which the depletion of extracellular Mg2+ stimulates insulin secretion." (PMID 37443824, 2023). "Insulinomas express AMY, and AMY or islet amyloid polypeptide (IAPP) has been detected in endocrine tumors (e.g., pancreatic tumors producing insulin or glucagon) and human pancreas." (PMID 36980580, 2023). "The ER Ca2+ channel ryanodine receptor 2 (RyR2) is required for maintenance of insulin content and glucose-stimulated insulin secretion, in part, via regulation of the protein IRBIT in the insulinoma cell line INS-1." (PMID 37141277, 2023). "There is an abundant expression of Klotho in the insulinoma β cells in mouse pancreatic islets (MIN6 β cells), and its silencing/overexpression significantly reduces/increases glucose-stimulated insulin production in MIN6 β cells." (PMID 36440221, 2022).
insulinoma (continued). "To this purpose, we used the rat insulinoma cell line INS1E, which is characterised by features of normal pancreatic beta cell (i.e., a high insulin content and responsiveness to glucose within the physiological range)." (PMID 36142530, 2022). "The insulinoma β-TC6 cells were trapped in the copolymer microcapsules by use of temperature sensitivity, and then growth, proliferation, and glucose-responsive insulin secretion of microencapsulated cells were successively monitored." (PMID 35268787, 2022). "We cotransfected Kir6.2-A28V with hemagglutinin (HA)-tagged SUR1 to express mutant KATP channels in rat insulinoma INS-1 cells, a rat insulinoma cell line that still maintains specific beta-cell physiology and insulin secretion." (PMID 35398096, 2022). "In the glucose analog 2-DG-treated rat insulinoma INS-1E cells, melatonin reduces insulin production via ER stress-induced autophagy." (PMID 33789681, 2021). "It has been demonstrated in INS-1 832/13 insulinoma cells that MCU and MICU1 play a role in metabolic coupling; reduced expression of either decreases mitochondrial Ca2+ uptake and inhibits insulin secretion." (PMID 33932586, 2021). "Considering that mice derived from a cross between C3H and C57BL/6 strains are known to exhibit higher insulin secretory capacity than C57BL/6 mice, an IT6 male mouse of this hybrid background was used to isolate insulinomas, which were independently cultured." (PMID 33436850, 2021). "We used INS-1E rat insulinoma cells and MIN6 cells derived from a mouse insulinoma that display the β-cell characteristics, including insulin secretion in response to, e.g., glucose." (PMID 34571911, 2021). "To analyze the effects of OxLDL on insulin secretion, we used rat insulinoma cell line, an INS-1 cell that has a physiological insulin secretion stimulated by increasing glucose concentration." (PMID 34578896, 2021). "The next study demonstrated that V. opulus fruit juice and juice enriched with phenolics decreased glucose-stimulated insulin secretion in the mouse insulinoma cell line MIN6 and increased insulin secretion at low glucose concentrations." (PMID 34205673, 2021). "For our experiments we used the mouse insulinoma cell line MIN6, which has morphological characteristics of pancreatic β-cells and shows glucose-inducible insulin secretion comparable to cultured normal mouse islet cells." (PMID 35056914, 2021). "An insulinoma (INS) is a functioning NEN originating from the neuroendocrine islet cells or multipotent stem cells of the pancreas, that produces insulin independently of glucose level’s stimuli." (PMID 34199977, 2021). "Prior work has shown the inhibition of ADSL in an insulinoma cell line lowered S-AMP, an insulin secretagogue, to impair glucose-stimulated insulin secretion." (PMID 32589682, 2020). "A multi-parameter, high-content screening study reported that seven extracts, from a library of 1319 marine invertebrate extracts, reproducibly altered the promoter activity of insulin and/or PDX-1 in murine Min6 insulinoma pancreatic β-cells." (PMID 32847055, 2020). "In addition, the log2 3× increase in NFATC1 expression in insulinomas vs. beta cells, together with the hypomethylation of the multiple NFATC1 binding sites in the SYT8/TNNI2 region, suggests that insulin gene transactivation in insulinoma may employ transcriptional signals derived from NFATC1." (PMID 33060578, 2020). "For instance, in rat insulinoma cells, the overexpression of UCP-1 prevents glucose-induced ATP increase, thereby limiting their glucose-stimulated insulin release capacity." (PMID 31366145, 2019). "Immunofluorescence staining of the Matrigel platforms harvested on day 18 after transplantation revealed newly differentiated insulin and GFP double positive cells only in the Matrigel platforms containing CM of syngeneic MIN-6 insulinoma cells." (PMID 30926860, 2019).
insulinoma (continued). "In the rat insulinoma cell line INS-1E and in primary mouse and rat pancreatic beta cells, use of FCCP/CCCP inhibits glucose-stimulated insulin release (GSIS)." (PMID 31366145, 2019). "Previous reports showed that caffeic acid enhanced glucose uptake in tumor necrosis factor α-treated insulin-resistant FL83B cells and human skeletal muscle cells (SkMC C-12580), and increased insulin secretion in rat insulinoma cells (INS-1E)." (PMID 30841887, 2019). "Firstly, to analyze the effects of E2 (an ER agonist) on insulin mRNA expression, we performed northern blotting analysis of total RNA from HIT-T15 insulinoma cells incubated for 48 h with E2." (PMID 30790128, 2019). "Cell division control protein 42 (Cdc42) and the microRNA (miRNA) miR-29 have important roles in β-cell proliferation and glucose-stimulated insulin secretion (GSIS), which we further explored using the mouse insulinoma cell line MIN6." (PMID 31662747, 2019). "In rat insulinoma cells and primary mouse and rat pancreatic beta cells, FCCP/CCCP inhibits glucose-stimulated (and Ca2+-dependent) insulin release (GSIS)." (PMID 31366145, 2019). "The expression of C peptide and insulin proteins in pulp, papilla, and follicle tissues derived differentiated MSCs was comparable to that in INS-1 rat insulinoma cells as revealed by immunocytochemical analysis." (PMID 31015367, 2019). "Glucose-stimulated insulin secretion increased with the high dosage of BA730-W and BA730-E in insulinoma cells, compared to the control." (PMID 30380669, 2018). "Lim, et al17 exposed cultured insulin producing RINm5F and HIT‐T15 insulinoma derived β‐cells to glucotoxic and lipotoxic conditions in the presence of absence of 100 nmol/L mitoQ." (PMID 29864244, 2018). "To ask if Adrb2 directly suppresses insulin, we stimulated cultured MIN6 cells, an insulinoma-derived cell line analogous to β-cells, with epinephrine or norepinephrine, the endogenous ligands for Adrb2, or salbutamol, an Adrb2-specific agonist." (PMID 30303066, 2018). "The net FASIS in model pancreatic β-cells, insulinoma INS-1E cells, provides >3 times more insulin than GSIS." (PMID 29921789, 2018). "In other mouse models of PanNETs21,24,25, MEN1 deletion using the insulin or PDX1 promoter driven Cre construct, insulinomas, glucagon-expressing tumors and well differentiated PanNETs were also observed." (PMID 30315258, 2018). "The rat insulinoma INS-1 cell line, which is widely used in insulin secretion studies, has been used as a model for the in vitro study of biological activities of tigerinin analogs." (PMID 29360748, 2018). "In addition, unlike the normal individuals, the endogenous ENPP1 protein levels were similar among insulinoma patients except in one case, consistent with our hypothesis of the suppressive effect of high level of endogenous insulin on Enpp1 expression in these patients." (PMID 29513794, 2018). "Multiple regression analysis showed that fasting insulin (β = 0.80, P = 0.003) was an independent predictor of serum FGF21 levels in subjects with insulinoma." (PMID 28225059, 2017). "Blood tests for insulinoma were requested, with the following results: fasting plasma glucose (FPG) = 51 mg/dL and immunoreactive insulin (IRI) = 12.7 μU/mL." (PMID 27478670, 2016). "We determined how 2-DG and/or melatonin affected known regulators of insulin signaling, phosphoinositide 3-kinase (PI3K), Akt/PKB, and mTOR, in rat insulinoma INS-1E cells." (PMID 27493704, 2016). "In this study, we provide the first demonstration that 2-DG reduces intracellular insulin which was increased by melatonin via autophagy and EDC3 in insulinoma INS-1E cells." (PMID 27493704, 2016). "To follow this, we transduced an insulinoma cell line with the 3-repeat domain MAPT, namely, MAPT3 (381aa) isoform, to test its effect on insulin secretion." (PMID 26824039, 2016). "In the rat insulinoma cell line (INS-1 832/13), BPA (10 and 100 nM) increased basal insulin secretion after short-term treatment (2 h)." (PMID 27782064, 2016).
insulinoma (continued). "Another study proposed that American ginseng root (25 μg/mL) stimulated insulin production and prevented cytokine-induced apoptosis via regulation of uncoupling protein-2 in INS-1 cells, a rat insulinoma cell line." (PMID 26587047, 2015). "The inadequate control of insulin secretion by somatostatin analogs is probably a consequence of the low expression of SSTR2 and SSTR5 in insulinomas, which also explains the reason for the low percentage of SPECT scintigraphy-positive tumors." (PMID 25298880, 2014). "Therefore, altered ADP- and GDP-specific activities could directly affect mtDNA replication or might have broader regulatory effects, much like those demonstrated with glucose-stimulated insulin secretion in an insulinoma cell line and isolated rat islet cells." (PMID 24271779, 2014). "Previous reports show improved insulin production and GSIS following PI formation in high passage insulinoma cells." (PMID 24015227, 2013). "MIN6 cells, a transformed β-cell line derived from a mouse insulinoma, retain GSIS and are a popular in vitro model for insulin secretion." (PMID 23560115, 2013). "Alx3, originally isolated from the hamster insulinoma cell line HIT-T15, participates in regulation of insulin gene expression in pancreatic β-cells through transactivation of the insulin promoter by acting on the E2A3/4 enhancer in cooperation with E47/Pan1." (PMID 23825702, 2013). "To examine the function of endogenous Sec5 on whole β cell insulin granule pool exocytotic kinetics, we employed the shRNA lentiviral technique to deplete endogenous Sec5 protein in the INS-1 832/13 insulinoma cell line." (PMID 23844030, 2013). "To further characterize the regulation of NKp46 ligand expression we stained the insulinoma cell lines INS-1E and MIN6 with anti-insulin and with NKp46-Ig (red and green respectively)." (PMID 24009765, 2013). "Our results support the notion that β2-syntrophin restrains the mobility of cortical granules in insulinoma INS-1 cells, thereby reducing insulin secretion and increasing insulin stores in resting cells, while increasing insulin release upon stimulation." (PMID 20886068, 2010). "To study the function of pericentrin in insulin secreting cells, we depleted pericentrin in pancreatic islets and MIN6 insulinoma cells using RNAi." (PMID 20676397, 2010). "The rationale for this test is that calcium stimulates insulin production from insulinoma and nesidioblastosis cells but not from normal beta-cells." (PMID 40395710, 2025). "SACST also failed to localize the insulinoma, as insulin secretion was not induced by stimulation from any arteries." (PMID 40405975, 2025). "Elevated insulin alongside low plasma glucose without ketosis remains a defining feature of insulinoma and serves as a critical indicator in differentiating insulinoma from other hypoglycemic etiologies such as reactive hypoglycemia and adrenal insufficiency." (PMID 40124204, 2025). "Here, along similar GCG-INS axes, we have shown the insulin-expressing cells from the canine insulinoma samples examined show strong expression of INS and no expression of GCG, consistent with their clinical classification as insulinomas." (PMID 40438247, 2025). "Negative insulin autoantibodies and routine pancreatic imaging excluded insulinoma and autoimmune hypoglycemia." (PMID 41367853, 2025). "Uncontrolled insulin hypersecretion in insulinoma is an autonomous process, independent of glucose or other regulatory hormones." (PMID 41488138, 2025). "Insulinoma is a notable consideration, a rare pancreatic tumor that secretes insulin independent of glucose levels, but the low insulin and C-peptide levels observed in this patient make this less likely." (PMID 39463547, 2024). "Insulinoma cells emit insulin continuously, independent of glucose concentration, in contrast to normal beta cells, which adjust insulin secretion in response to blood glucose levels." (PMID 39723310, 2024).